BDNF (brain derived neurotrophic factor)
Diseases named in the same sentence as BDNF in open-access papers (continued):
Sharing a sentence is not in itself a finding about the gene and the disease.
depression (continued). "In addition, berries and other high-flavonoid foods have been shown to improve measures of cognitive performance (such as executive function, which is often impaired in depression) and increase peripheral levels of BDNF with chronic administration." (PMID 38300292, 2024). "Since BDNF supports memory formation and is often reduced in cognitive decline and depression, our findings suggest that its upregulation by NN may be one of the plausible mechanisms for improving UCMS-induced cognitive impairment and depression." (PMID 39796528, 2024). "Negative changes in microbiome diversity and taxonomic abundance can promote depression by increased intestinal barrier permeability, systemic inflammation, changes in tryptophan biometabolism as well as changes in brain‐derived neurotrophic factor (BDNF)." (PMID 39470120, 2024). "Notably, phloridzin treatment also reversed the decrease in key biochemical markers associated with depression (GSH, BDNF, TrkB, CREB, ERK)." (PMID 39478958, 2024). "In addition to AERE, RE was identified as the second most effective intervention for increasing BDNF levels in patients with depression." (PMID 40226670, 2024). "Following ketamine treatment, the cleavage of pro‐BDNF in the hippocampus significantly increased, suggesting that pro‐BDNF is related to the occurrence of depression and may be an indicator of antidepressant efficacy." (PMID 39639753, 2024). "In the pathophysiology of depression, SCFAs affect epigenetic mechanisms; participate in reducing the production of proinflammatory cytokines, the maturation of microglia and BDNF production; strengthen the protective barrier of the epithelium; and stimulate the vagus nerve." (PMID 38891970, 2024). "To further examine the function of BDNF, we used a pharmacological approach to determine whether restoration of BDNF in this circuit would be sufficient to reverse depression‐like behaviors." (PMID 38155473, 2024). "Understanding the relationship between the plasma neurofilament light chain (NfL) and brain-derived neurotrophic factor (BDNF) may help us to better understand the mechanisms of depression." (PMID 38255209, 2024). "Regrettably, current research does not conclusively establish a relationship between the BDNF Val66Met polymorphism and body weight in patients with coexisting diabetes mellitus and depression." (PMID 38988887, 2024). "Moreover, the effect of BDNF Met is predominantly focused on depression, while the effect on other NPS remains understudied." (PMID 38279143, 2024). "The long-term effects of developmental stressors on the BDNF/TrkB system and GR activity in the prefrontal cortices have also been argued to understand the possible pathogenesis of neuropsychiatric illnesses, including depression." (PMID 38338875, 2024). "The study of BDNF is useful not only in the search for potential biomarkers for the improvement of psychiatric disorders, but also as a direct indicator of the importance of neuroplasticity and neurotrophism for the understanding and treatment of depression." (PMID 39684808, 2024). "On the other hand, hypomethylation might result in the enhanced expression of the BDNF precursor, proBDNF, which is known to be conducive to neurodegeneration and depression." (PMID 38542252, 2024). "Therefore, empagliflozin can potentially improve depression symptoms by directly influencing the BDNF system, and indirectly affecting cognitive functions through GABA activation." (PMID 38408937, 2024). "BDNF plays a pivotal role in the onset, progression, and treatment of depression." (PMID 39654620, 2024). "Therefore, targeting the A1/A2 astrocytic balance and enhancing BDNF signaling within astrocytes provide a promising therapeutic strategy for treating major depressive disorder and other conditions where neuroplasticity is impaired." (PMID 39650796, 2024).
depression (continued). "While markers such as IL-6, TNF-alpha, and CRP have well-established relationships with depression in cancer patients, the present study focuses on IL-4, BDNF, and neopterin due to their unique and potentially significant roles in the inflammatory and neurotrophic pathways." (PMID 39355088, 2024). "Moreover, in de-ovulated model mice, the detection of CREB and eukaryotic translation elongation factor 2 (eEF2) suggested that Ber (10 mg/kg) can improve depression through the BDNF/CREB/eEF2 pathway, and the onset of action is 2–4 weeks faster than SSRI." (PMID 38318145, 2024). "The other three studies looked at the BDNF-depression pair in stroke patients." (PMID 39568824, 2024). "However, “Anxiety”, “NMDA receptor blockade”, “Antidepressant”, “Oxidative stress”, “Treatment resistant depression”, “Ketamine” and “BDNF” have been the keywords with the strongest citation bursts in recent years." (PMID 38974036, 2024). "SSA has been shown to not only ameliorate depression-like behavior following cerebral ischemia through the cAMP-response element binding protein (CREB)/BDNF pathway and inhibit apoptosis of hippocampal neurons, but also alleviate perimenopausal depression-like symptoms." (PMID 38675471, 2024). "Reduced levels of BDNF are thought to contribute to the onset and progression of depression." (PMID 39770546, 2024). "On the other hand, stimulation of the BDNF signaling pathway can enhance sucrose preference, anxiolytic-like activities, and related learning and memory in a variety of depression models, indicating that stimulating BDNF signaling exhibited strong neurobehavioral modulating effects." (PMID 40255947, 2024). "Therefore, inhibition of central classical RAS by ARBS and ACEIs and activation of non‐classical RAS prevent the development of depression by regulating 5HT, BDNF, mitochondrial dysfunction, oxidative stress, and neuroinflammation." (PMID 37953501, 2024). "Hence, irisin function in the brain can be placed at the intersection between its neuroprotective anti-inflammatory activity, the activation of BDNF signaling, AD pathogenesis, and depression." (PMID 39769243, 2024). "Additionally, the signaling pathways mediated by BDNF and its receptor TrkB play key roles in the pathophysiology of depression and the therapeutic mechanisms of antidepressant drugs." (PMID 39648800, 2024). "This inhibition shifts microglia from a pro-inflammatory state to a more neuroprotective phenotype and leads to increased BDNF synthesis, reduced synaptic pruning, and decreased neuronal apoptosis, ultimately promoting neuroprotection and alleviating depression-like behaviors." (PMID 39204578, 2024). "Additionally, IGF2 influences various brain functions including memory, depression, and autism and impacts the expression of BDNF." (PMID 39319049, 2024). "One hypothesis suggests that depression arises when neuroplasticity decreases as a result of deficits in the neurotrophic support provided by brain-derived neurotrophic factor (BDNF)." (PMID 38337395, 2024). "Exercise may alleviate depression through common neuromolecular mechanisms such as increased expression of neurotrophic factors [i.e., brain-derived neurotrophic factor (BDNF)], among others." (PMID 38533447, 2024). "Since it plays a role in reorganisation of the brain microenvironment, BDNF may prove useful in the treatment of memory and depression and in understanding the pathogenesis of brain tumours." (PMID 39598176, 2024). "For decades now, scientists have been researching BDNF as a potential biomarker for depression." (PMID 39201490, 2024). "Furthermore, various treatments for depression, such as antidepressants, show an increase of BDNF expression in the brain." (PMID 39839132, 2024). "Targeting biomarkers such as neopterin, IL-4, and BDNF may help in the management of depression in lymphoma patients undergoing chemotherapy." (PMID 39355088, 2024). "Previous studies have shown an etiological link between depression and BDNF." (PMID 39902245, 2024).
depression (continued). "Numerous clinical studies highlighted the protective and therapeutic role of neuroactive probiotics in reducing the inflammatory cascade and kynurenine levels and increasing BDNF expression via a functional crosstalk between the gut–brain axis in major depressive disorders." (PMID 38671931, 2024). "Moreover, insomnia is a common characteristic among individuals with depression, and research also indicates a link between BDNF levels and sleep disturbances." (PMID 39767653, 2024). "Intriguingly, antidepressant-like effects of mGlu2 antagonists in mouse models of depression seem to involve BDNF release, whereas we show in the present study that mGlu2 agonists transactivate TrkB in healthy mice through a distinct mechanism that is independent of BDNF release." (PMID 38277461, 2024). "In the context of treatment-resistant depression, BDNF may play a crucial role in response to novel antidepressant treatments such as ketamine." (PMID 39769420, 2024). "This hypothesis emphasizes that a reduction in BDNF levels is central to the onset of depression, leading to neuroplastic changes." (PMID 39355088, 2024). "While identifying depression-related genes like BDNF has been a useful strategy, we argue that research should also explore genes linked to the physiological changes occurring before, during, and after pregnancy to better capture the unique female-specific aspects of PPD." (PMID 39588356, 2024). "Additionally, ethanol extract from HCB has been shown to upregulate BDNF and TrkB receptor proteins in the hippocampus of rats, alleviating depression-like behaviors." (PMID 39770546, 2024). "Moreover, through protein-protein interactions, FKBP51 influences the signaling of other depression-relevant pathways, such as GSK3β, BDNF, and nuclear factor kappa B, thereby connecting it to inflammation, the immune system, and autophagy." (PMID 38916735, 2024). "Platelets are widely regarded as a peripheral model of neuronal activity in neuropsychology, and depletion of platelets may affect BDNF and serotonin level expression, thereby affecting the occurrence and development of depression." (PMID 39655209, 2024). "As reported, the regulation of BDNF is essential for the pathophysiology of depression and related brain functions in which epigenetic alterations of the BDNF gene may be involved; BDNF methylation has the potential to be a biomarker of depression." (PMID 38818577, 2024). "Similarly, in a chronic mild stress (CMS) depression model, Rg1 upregulated the hippocampal BDNF signaling pathway." (PMID 39639753, 2024). "Optical spectroscopy also showed that red beans contain zinc, which may increase BDNF and help in treating depression." (PMID 38690099, 2024). "In depression pathogenesis, elevated levels of proinflammatory cytokines in the brain are recognized for their role in impairing neuronal function by reducing the expression of BDNF." (PMID 39061415, 2024). "In summary, these results were the first to suggest that the downregulation of BDNF in the LC–dLS circuit represents an endophenotype for chronic stress‐induced depression and shows the essential role of BDNF‐TrkB signaling within this circuit in conferring resilience to stress." (PMID 38155473, 2024). "We concluded that decreased methylation in the BDNF exon IV promoter could be considered as a biomarker of a depression state among adolescent girls." (PMID 38542252, 2024). "Several studies using various animal models of depression and cognitive impairment have reported that resveratrol treatment alleviates cognitive deficits and reductions in BDNF and pCREB/CREB levels, likely through the modulation of neuroinflammation and the activation of the Sirt1/miR-134 pathway." (PMID 39684486, 2024). "Based on these studies, there is preliminary evidence that YBIs may be associated with increased serum brain-derived neurotrophic factor (BDNF) and reduced serum cortisol and interleukin-6 (IL-6) in patients with depression." (PMID 38928543, 2024).
depression (continued). "Counterintuitively, we found hypomethylation in the BDNF gene to be associated with depression rather than hypermethylation, which is known to repress protein expression." (PMID 38542252, 2024). "Our data indicated a substantial increase in BDNF expression and enhanced ratios of phosphorylated TrkB (p-TrkB) to TrkB, as well as phosphorylated AKT (p-AKT) to AKT in both the hippocampus and cortex of mice afflicted with depression after treatment with RVG-BDNF-Exos." (PMID 41221079, 2024). "However, an experiment in a mouse model of corticosterone-induced depression found that overactive neuronal autophagy depleted BDNF and impaired adult hippocampal neurogenesis." (PMID 39057075, 2024). "Apigenin increases the neurotrophic activities of BDNF (brain-derived neurotrophic factor) through direct binding, which may serve as a possible treatment for its curative efficiency in neurodegenerative diseases and depression." (PMID 39771214, 2024). "In terms of neuroprotection, it has been suggested that low levels of brain-derived neurotrophic factor (BDNF) could play a key role in the pathogenesis of depression and anxiety disorders." (PMID 40226680, 2024). "Research has linked BDNF signaling and Val66Met polymorphisms to functional alterations in the anterior but not posterior cingulate cortex across major depressive disorders as well as normative conditions." (PMID 38916728, 2024). "Furthermore, BDNF is correlated with specific presentations in PD patients like restless leg syndrome and depression." (PMID 38752280, 2024). "In addition, Zn deficiency has been associated with major depression and higher Zn serum concentrations with a lower rate of symptoms related to depression and anxiety, due to deficits serotonergic system, BDNF, and neurogenesis." (PMID 38707461, 2024). "Currently, the limited number of studies suggests the need for further research, including larger sample sizes and investigations of BDNF and intranasal esketamine, which has been approved by several regulatory agencies for the treatment of treatment-resistant depression." (PMID 39684808, 2024). "BDNF binds mainly to tropomyosin-related kinase B receptors (TrkB), which have anti-apoptotic properties and inhibit depression in the long term, whereas pro-BDNF preferentially binds to the p75NTR receptor and promotes neuronal apoptosis and long-term depression." (PMID 39430530, 2024). "In a randomized experiment, the probiotic combination of B. lactis, B. bifidum, L. acidophilus, and B. longum with the synbiotics FOS, GOS, and inulin decreased depression and raised blood levels of a brain-derived neurotrophic factor in depressed patients compared to controls." (PMID 38404464, 2024). "Evidence suggests that the lack of BDNF plays a significant role in the pathophysiology of depression, and exercise-induced increases in BDNF can improve hippocampal atrophy, consequently enhancing cognitive functions such as memory, thus supporting the notion of reducing depression." (PMID 39444807, 2024). "Dysregulation of brain RAS triggers the development and progression of depression through the reduction of brain 5HT and expression of brain‐derived neurotrophic factor (BDNF) and the induction of mitochondrial dysfunction, oxidative stress, and neuroinflammation." (PMID 37953501, 2024). "Also, clinical and preclinical research demonstrates that the alteration of BDNF/TrkB-mediated signaling is involved in the pathology of depression." (PMID 38338875, 2024). "For example, reduced histone acetylation at the promoters of neurotrophic factor genes, such as brain-derived neurotrophic factor (BDNF), may compromise synaptic plasticity and neuronal survival pathways implicated in depression pathophysiology." (PMID 38792892, 2024). "Physical activity boosts brain-derived neurotrophic factor (BDNF), promoting neuroplasticity, and consequently enhancing memory and learning, while also offering protection against Alzheimer’s and depression." (PMID 39734666, 2024).
depression (continued). "Furthermore, MDD patients with suicidal depression tend to have lower serum levels of brain-derived neurotrophic factor (BDNF) compared to the general population." (PMID 38773479, 2024). "In this sense, the hypothesis could be considered that patients with a depressive syndrome could have a better response to antidepressant treatment if they have higher levels of BDNF in specific areas of the central nervous system, such as the hippocampus." (PMID 39408702, 2024). "Also, our results made clear that the supplementation improved the Bifidobacterium genera abundance, which is recognized as a BDNF stimulant and has been applied as probiotics for BDNF enhancement in mental illnesses like anxiety and depressive disorder." (PMID 39339649, 2024). "Depression disorders are linked to decreased levels of brain-derived neurotrophic factor (BDNF), which is controlled by the cyclic adenosine monophosphate (cAMP)-cAMP response element binding protein (CREB)-BDNF signaling pathway." (PMID 38399736, 2024). "Therefore, the appraisal of peripheral BDNF, in the context of determining so-called inflammation/metabolic “signatures” in depression, is still considered important and very challenging." (PMID 37511930, 2023). "The BDNF level decreases in depression and is reversed with antidepressants." (PMID 37654035, 2023). "A human study has indicated that the BDNF Promoter IV may play a role in the development of depression." (PMID 37189402, 2023). "Considering contradictory findings of previous investigations and growing prevalence of psychological disorders, we decided to investigate association between dietary total fat and omega-3 fatty acids intake with serum BDNF levels, depression, anxiety and psychological distress in Iranian adults." (PMID 37012351, 2023). "Disruption of early life commensal-dependent HPA axis development may contribute to depression through BDNF suppression." (PMID 37152431, 2023). "Interestingly, fecal microbiota transplantation for the treatment of depression in rats exerted an antidepressant effect by increasing the expression levels of BDNF and other components such as serotonin." (PMID 37631295, 2023). "Considering that Shiikuwasha peel and pulp extracts elicited an approximately twofold higher effect on ACHN cells, and BDNF is largely synthesized in the kidney, Shiikuwasha may be useful as a prophylactic and therapeutic agent against depression." (PMID 38082356, 2023). "According to the neuroplasticity hypothesis of depression, chronic stress leads to sustained decreases in neuroprotective factors [e.g., brain-derived neurotrophic factor (BDNF) expression and signaling]." (PMID 37046299, 2023). "In individuals suffering from major depressive disorder, an increase in BDNF was associated with longer non-rapid eye movement sleep duration as well as slow-wave activity." (PMID 36984890, 2023). "Flaxseed oil supplementation may be related to brain-derived neurotrophic factor (BDNF) and the psychological status of women with depression." (PMID 36766971, 2023). "It has been reported that vitamin D may affect depression by increasing BDNF, which plays an important role in the survival, differentiation, and function of newborn neurons in the adult hippocampus." (PMID 38201927, 2023). "Emerging evidence further implicates BDNF in the pathophysiology of depression." (PMID 36766691, 2023). "Blood serum analyses of depressed patients also show reduced BDNF levels before treatment, but additionally that these reduced levels can be rescued by antidepressant treatments, supporting that BDNF is a biomarker of depression and treatment response." (PMID 37614344, 2023). "Several studies agree that BDNF serum levels fail to act as biomarkers for anxiety since dysregulated expression of this factor is present in multiple psychiatric illnesses including depression and schizophrenia." (PMID 35998298, 2023).